FXN (frataxin)
Diseases named in the same sentence as FXN in open-access papers (continued):
Sharing a sentence is not in itself a finding about the gene and the disease.
Friedreich ataxia (continued). "We identified 49 patients (31 families) carrying mutations in the FXN gene responsible for Friedreich ataxia (FRDA), in accordance with epidemiological data acknowledging Friedreich ataxia as the most common form of autosomal recessive ataxia in Europe." (PMID 26068213, 2015). "Friedreich ataxia (FRDA) is the most frequent autosomal recessive ataxia (2–4 cases/100,000), caused by a GAA expansion in the first intron of the frataxin (FXN) gene, which encodes a mitochondrial protein involved in iron-sulfur cluster biogenesis." (PMID 24787137, 2014). "Friedreich ataxia (FRDA) is a fatal, autosomal recessive neurodegenerative disorder caused by homozygous GAA repeat expansion within intron 1 of the FXN gene." (PMID 24971578, 2014). "Our study shows that RNA/DNA hybrids (R-loops) form on expanded repeats of endogenous FXN and FMR1 genes, associated with Friedreich ataxia and Fragile X (FXS) disorders, in patient cells." (PMID 24787137, 2014). "Friedreich ataxia (FRDA) is an autosomal recessive neurodegenerative disorder, caused by a GAA repeat expansion mutation within intron 1 of the FXN gene, resulting in reduced levels of frataxin protein." (PMID 25198290, 2014). "Friedreich’s ataxia (FRDA) is a hereditary neurodegenerative disease characterized by a reduced synthesis of the mitochondrial iron chaperon protein frataxin as a result of a large GAA triplet-repeat expansion within the first intron of the frataxin gene." (PMID 24714088, 2014). "In fact, transcript expression of frataxin is highly correlated with that of PGC-1α in Friedreich Ataxia and control cells, and knock down of frataxin in cell culture also decreases transcript expression of PGC-1α." (PMID 25610371, 2014). "Friedreich ataxia (FRDA) is an autosomal recessive neurodegenerative disorder, caused by a GAA repeat expansion mutation within intron 1 of the FXN gene." (PMID 25198290, 2014). "This gene may contribute to the functional effects of frataxin deficiency and the clinical manifestations of Friedreich ataxia (FA)." (PMID 23844591, 2013). "In this context, we provide the first systematic analysis of the FXN 3′-UTR in patients with Friedreich ataxia and its regulation on frataxin levels." (PMID 23382970, 2013). "Cells actively build and deliver ISCs to target proteins; defects in this process lead to disease, notably Friedreich’s ataxia, which is caused by the expansion of a GAA trinucleotide repeat element in an intron of the human frataxin gene." (PMID 23444034, 2013). "The only Drosophila ISC biosynthetic protein studied to date is frataxin, in attempts to model Friedreich’s ataxia, a disease arising from reduced expression of the human frataxin homologue." (PMID 23444034, 2013). "“Frataxin fracas” were the words used when referring to the frataxin-encoding gene (FXN) burst in as a motive to disqualify an alternative candidate gene, PIP5K1B, as an actor in Friedreich's ataxia (FRDA)." (PMID 24194977, 2013). "To illustrate the cardiovascular consequences of this post-transcriptional regulation, we will focus on Friedreich ataxia (FRDA), which is an autosomal recessive neurodegenerative disease arising from mutations in both alleles of the frataxin gene (FXN)." (PMID 24065925, 2013). "Gain of magnetism was seen with loss of YFH1, which has been reported to accumulate iron in mitochondria, and whose human homolog FXN is responsible for the neurodegenerative disease Friedreich's ataxia." (PMID 22389629, 2012). "For example, 4b treatment reverses FXN gene silencing in primary cells from Friedreich's ataxia patients and relieves disease phenotype and transcriptional abnormalities in HD transgenic mice." (PMID 22363205, 2012). "Recently many studies suggest that Friedreich ataxia is an epigenetic disorder (see review) and HDAC inhibitors correct frataxin deficiency." (PMID 23082224, 2012).
Friedreich ataxia (continued). "4b treatment reverses FXN gene silencing in primary cells from Friedreich's ataxia patients and relieves disease phenotype and transcriptional abnormalities in HD transgenic mice." (PMID 22363205, 2012). "In this report, we describe a new synthetic route to a class of benzamide HDAC inhibitors that show efficacy in restoring transcription to the silenced FXN gene in primary lymphocytes from Friedreich's ataxia patients." (PMID 27721337, 2011). "CTCF has also recently been shown to be involved in the epigenetic regulation of frataxin (FXN), a gene mutated and silenced in Friedreich ataxia, which causes progressive damage to the nervous system." (PMID 21813016, 2011). "Friedreich's ataxia (FRDA) is a mitochondrial rare disease, which molecular origin is associated with defect in the expression of frataxin." (PMID 21687738, 2011). "By providing new mechanistic insights into the molecular factors influencing frataxin expression, our results should aid in the discovery of new therapeutic targets for the treatment of Friedreich ataxia." (PMID 20808827, 2010). "As expected, frataxin mRNA levels were reduced in the Friedreich ataxia patient lymphoblasts as compared to the control lymphoblasts, while SRF mRNA expression levels were only moderately different between the two cell lines." (PMID 20808827, 2010). "Over-expression of either of these two transcription factors led to a significant increase in frataxin mRNA levels in Friedreich ataxia patient lymphoblasts." (PMID 20808827, 2010). "Friedreich's Ataxia (FRDA), the most prevalent form of inherited neurodegenerative diseases, is caused by severely reduced expression of frataxin." (PMID 21084725, 2010). "Characterization of the regulatory elements controlling frataxin expression is critical in the development of therapies directed at restoring frataxin expression levels in Friedreich ataxia patients." (PMID 20808827, 2010). "Expression of recombinant transcription factors SRF or TFAP2 in two distinct human cell lines, as well as in Friedreich ataxia patient lymphoblasts, resulted in increased frataxin mRNA levels." (PMID 20808827, 2010). "Recently, a study employing an experimental histone deacetylase (HDAC) inhibitor in a mouse model of Friedreich ataxia revealed that this drug can substantially increase frataxin mRNA and protein levels." (PMID 20808827, 2010). "Frataxin levels in Friedreich ataxia patients vary from between 5% and 30% of normal levels, while healthy heterozygous carriers typically express more than 50% of normal frataxin levels." (PMID 20808827, 2010). "The typical molecular basis of Friedreich ataxia is the expansion of a GAA trinucleotide repeat in both copies of the FXN gene." (PMID 20979606, 2010). "Our findings provide a mechanistic basis for the transcriptional silencing of the FXN gene in Friedreich ataxia that is consistent with this response to HDAC inhibitors, and elucidate a rational basis for their action." (PMID 19956589, 2009). "Friedreich ataxia (FRDA) patients are homozygous for an expanded GAA triplet-repeat sequence in intron 1 of the FXN gene." (PMID 19956589, 2009). "We treated KIKI mice with a novel histone deacetylase inhibitor, compound 106, which substantially increases frataxin mRNA levels in cells from Friedreich ataxia individuals." (PMID 18463734, 2008). "All Friedreich ataxia patients carry a GAA⋅TTC repeat expansion in the first intron of the frataxin gene, either in the homozygous state or in compound heterozygosity with other loss-of-function mutations." (PMID 18463734, 2008). "Control and Friedreich's ataxia patient cultured skin fibroblasts, frataxin-depleted neuroblastoma-derived cells (SK-N-AS) were studied for their response to iron chelation, with a particular attention paid to iron-sensitive aconitase activity." (PMID 18558000, 2008).
Friedreich ataxia (continued). "The defective protein in Friedreich ataxia, frataxin, is a small protein of the mitochondrial matrix for which several functions in the mitochondria have been proposed." (PMID 17112370, 2006). "The use of EPO in the treatment of Friedreich ataxia is based on the increased in vitro frataxin expression in response to EPO." (PMID 17112370, 2006). "We present Friedreich ataxia patients with frataxin gene deletions." (PMID 42227166, 2026). "To test whether lowering FDX2 levels could also improve disease phenotypes in a mouse model of Friedreich’s ataxia, we asked whether a 50% decrease in Fdx2 gene dosage would suppress the movement disorders of a frataxin mouse mutant." (PMID 41372402, 2026). "Friedreich’s ataxia (FRDA) is another autosomal-recessive inherited neurodegenerative disease, and the most common ataxia caused by mutation in the FXN gene, resulting in deficiency of the mitochondrial protein frataxin." (PMID 40507855, 2025). "Friedreich ataxia (FRDA) is a multisystemic, life-shortening, autosomal recessive degenerative disorder caused primarily by biallelic GAA repeat expansions in the first intron of the FXN gene." (PMID 39907933, 2025). "Similarly, Friedreich’s ataxia involves optic atrophy alongside spinocerebellar degeneration due to a GAA trinucleotide repeat expansion in the nuclear FXN gene." (PMID 40332750, 2025). "Friedreich’s ataxia (FRDA) is an autosomal recessive neurodegenerative disease resulting from a homozygous GAA trinucleotide repeat expansion within the first intron of the frataxin (FXN) gene." (PMID 38929088, 2024). "Friedreich's ataxia (FRDA) is a rare genetic disorder characterized by motor discoordination and cerebellar involvement due to mutations in the frataxin (FXN) gene, which encodes a mitochondrial protein involved in iron-sulfur cluster biogenesis and iron handling." (PMID 39100202, 2024). "Lack of FXN is known to cause mitochondrial dysfunction and Friedreich’s ataxia, a recessive neurodegenerative disorder commonly associated with hypertrophic cardiomyopathy." (PMID 38564291, 2024). "Further, it clarifies the molecular role of FXN in this process, which may be relevant to the development of treatments for Friedreich’s ataxia." (PMID 38627381, 2024). "The present meta-analysis explored the effect of different types of interventions targeting mitochondrial function, frataxin, or patients’ symptoms on clinical, cardiac, biochemical, PROMs, imaging, or neurophysiologic biomarkers in 1409 patients with Friedreich ataxia." (PMID 37889470, 2024). "Friedreich’s ataxia (FRDA) is recognized as an autosomal recessive disorder originating from reduced levels of frataxin (FXN, a mitochondrial iron chaperone protein), consequent to a large GAA triplet-repeat expansion within the first intron of the frataxin-encoding gene." (PMID 37242612, 2023). "Frataxin (FXN) is the protein missing in Friedreich’s ataxia." (PMID 37576821, 2023). "The intronic expansion in FXN (Friedreich ataxia), results in the decreased expression of frataxin, a protein involved in mitochondrial iron metabolism, and the ATM protein (ataxia–telangiectasia) is a powerful protein cinase, involved in the cellular response to genotoxic stress." (PMID 37048110, 2023). "Friedreich ataxia is the most common inherited ataxia in Europe and is mainly caused by biallelic pathogenic expansions of the GAA trinucleotide repeat in intron 1 of the FXN gene that lead to a decrease in frataxin protein levels." (PMID 38041144, 2023). "The implications of mitochondrial dysfunction and the mtUPR have also been described in Friedreich’s Ataxia (FA), a rare disease arising from a GAA repeat expansion in the frataxin (FXN) gene, which encodes the mitochondrial FXN protein involved in iron-sulfur cluster biosynthesis." (PMID 38136659, 2023).
Friedreich ataxia (continued). "Notably, DT-216, a PIP that facilitates the transcription of repressive GAA repeats to enhance frataxin expression in Friedreich’s ataxia, is currently undergoing phase I clinical trials (NCT05285540)." (PMID 37707954, 2023). "Interestingly, frataxin accumulation in treated patients’ cells is comparable to frataxin levels in cells from unaffected carrier sibling, suggesting a potential beneficial role of etravirine in a Friedreich ataxia therapy." (PMID 35221903, 2022). "Nrf2 expression induction has been detected to ameliorate the phenotypic defects observed in neural stem cells isolated from the embryonic cortex of frataxin knockin/knockout mice, re-establishing a proper neuronal differentiation program in Friedreich’s ataxia." (PMID 36078068, 2022). "Indeed, Friedreich’s ataxia mouse models have been treated with viral vectors en-coding for either FXN or neurotrophins, such as brain-derived neurotrophic factor showing promising results." (PMID 33670433, 2021). "Friedreich ataxia (OMIM code #22930) is a neurodegenerative disorder, inherited with an autosomal recessive pattern, caused by the homozygous GAA triplet repeat expansion in the FXN, which encodes for the protein frataxin." (PMID 33718303, 2021). "Friedreich's ataxia (FRDA) is a familial hereditary disorder involving the spinal cord and cerebellum, which is mainly caused by repeat amplification of homozygous guanine–adenine–adenine (GAA) triplet located in the frataxin gene." (PMID 35237223, 2021). "Moreover, fibroblasts collected from Friedreich’s ataxia patients, as well as FXN knockdown human fibrosarcoma HT-1080 cells, were considerably more sensitive to the administration of erastin, one of the best characterized ferroptosis activators." (PMID 33578654, 2021). "Friedreich ataxia (FRDA) is a progressive neurological and cardiac degenerative disease caused by repeated amplification of GAA in the first intron of two alleles of the FXN gene." (PMID 32372896, 2020). "Four patients with IMD were reported during the review of medical records: 1 patient with MELAS (m.3243A > G), 1 patient with Hurler disease (p.P533R/p.E178K in IDUA gene), and 2 patients with Friedreich’s ataxia (expansion of the number of GAA repeats in exon 1 of FXN gene)." (PMID 32143453, 2020). "The role of FXN in the β-cell is illustrated by patients with Friedreich’s ataxia." (PMID 33198243, 2020). "The common clinical symptoms of Friedreich’s ataxia (FRDA) include ataxia, muscle weakness, type 2 diabetes and heart failure, which are caused by impaired mitochondrial function due to the loss of frataxin (FXN) expression." (PMID 32269244, 2020). "We propose that this reconstitution recapitulates physiological conditions which provides a model for Fe-S cluster biosynthesis, clarifies the roles of FDX2 and FXN and may help develop Friedreich’s ataxia therapies." (PMID 31395877, 2019). "The ability to specifically quantify extra-mitochondrial and mitochondrial isoforms of frataxin in whole blood will make it possible to readily follow the natural history of diseases such as Friedreich’s ataxia and monitor the efficacy of therapeutic interventions." (PMID 30451920, 2018). "Friedreich ataxia (FRDA), the most common autosomal recessive hereditary ataxia, is majorly caused by homozygous expanded guanine-adenine-adenine (GAA) repeats in intron 1 of the frataxin (FXN) gene." (PMID 29125827, 2017). "Friedreich ataxia is a progressive neurodegenerative disease caused by the expansion of GAA trinucleotide repeats within the first intron of the FXN gene, which encodes frataxin." (PMID 28852135, 2017). "FXN was first identified for its connection to Friedreich's ataxia, a progressive neurodegenerative disease caused by an expansion of a GAA trinucleotide repeat within the first intron of the FXN gene, which results in reduced levels of FXN." (PMID 28349052, 2017).
Friedreich ataxia (continued). "Pathogenic expansion of both alleles of the GAA repeat present in the first intron of the Frataxin gene has been reported in the majority of cases with Friedreich’s ataxia; it contributes to the disease by prolonging transcription, resulting in a significant decrease in Frataxin protein levels." (PMID 28832669, 2017). "Friedreichs ataxia, the most common form of ataxia in humans, is caused by the expansion of a (GAA)n repeat in intron 1 of the Frataxin gene, which in turn results in transcriptional silencing, presumably because of the triplex-forming potential of the (GAA)n repeat." (PMID 26844769, 2016). "Finally, excising expanded GAA/TTC repeats in Friedreich Ataxia fibroblasts reactivated the expression of frataxin, improved the activity of the Fe-S-containing Aconitase, and increased cellular ATP levels." (PMID 27827362, 2016). "The humanized mouse model of Friedreich ataxia (YG8sR), which carries a single transgenic insert of the human FXN gene with an expanded GAA triplet-repeat in intron 1, is deficient for FXN transcript when compared to an isogenic transgenic mouse lacking the expanded repeat (Y47R)." (PMID 26393353, 2015). "Friedreich ataxia (FRDA), the most common autosomal recessive ataxia disorder, is caused by a dynamic GAA repeat expansion mutation within intron 1 of FXN gene, resulting in down-regulation of frataxin expression." (PMID 24971578, 2014). "Friedreich ataxia (FRDA) is an autosomal recessive disease characterised by neurodegeneration and cardiomyopathy that is caused by an insufficiency of the mitochondrial protein, frataxin." (PMID 25000412, 2014). "In this regard, we recently reported that in a cellular model of Friedreich's ataxia (which elicits oxidative damage) neurons responded to IGF-I only when they became frataxin deficient, but not under normal conditions." (PMID 24715976, 2014). "In the future, the involvement of miRNAs in a FRDA-specific regulation of frataxin may provide a rationale for miRNA-based therapies in Friedreich ataxia." (PMID 23382970, 2013). "Similarly, in Friedreich ataxia (FRDA), the pathogenic expanded (GAA·TTC)n sequence in intron 1 of the FXN gene undergoes progressive expansion in the cerebellum and dorsal root ganglia of FRDA patients and in a transgenic mouse model." (PMID 23071719, 2012). "And blood cells from Friedreich ataxia patients harbor frataxin deficiency without a loss of mitochondrial function." (PMID 23082224, 2012). "Friedreich ataxia (FRDA) is an inherited neurodegenerative disorder caused by GAA repeat expansion within the FXN gene, leading to epigenetic changes and heterochromatin-mediated gene silencing that result in a frataxin protein deficit." (PMID 21397024, 2011). "Friedreich Ataxia (FRDA) is an inherited autosomal recessive neurodegenerative disease in which over 96% of patients have a homozygous expansion of a GAA triplet repeat in the first intron of the frataxin (FXN) gene on chromosome 9." (PMID 21687738, 2011). "Friedreich ataxia patients show a marked decrease in both frataxin mRNA and protein levels." (PMID 20559546, 2010). "Finally, a ChIP experiment revealed that SRF occupancy of the FXN promoter was reduced in the Friedreich ataxia patient lymphoblasts as compared to the control lymphoblasts." (PMID 20808827, 2010). "Friedreich ataxia is a neurodegenerative disease caused by the lack of frataxin, a mitochondrial protein." (PMID 20111601, 2010). "Identification and further characterization of these two new factors involved in frataxin expression may aid in the development of new therapeutic avenues for the treatment of Friedreich ataxia." (PMID 20808827, 2010). "In a frataxin deficient mouse model and in Friedreich ataxia patient lymphoblast cells, heme production was not reduced, but the heme derivatives, mitochondrial heme A and heme C levels were decreased." (PMID 20862391, 2010).